MYDGF (myeloid derived growth factor)
Diseases named in the same sentence as MYDGF in open-access papers (continued):
Sharing a sentence is not in itself a finding about the gene and the disease.
tumor (continued). "Furthermore, MYDGF can also promote tumor angiogenesis, induce macrophages to chemotaxis into tumor tissue, and then release various inflammatory cytokines, including IL-6 and TNF-α, which ultimately aggravate inflammation of tumor microenvironment and accelerate HCC progression." (PMID 33391471, 2021). "Additionally, MYDGF could induce the chemotaxis of macrophages into tumor tissues and promote them releasing inflammatory cytokines, including IL-6 and TNF-α." (PMID 33391471, 2021). "For HCC itself or the tumor microenvironment, MYDGF might be a potential therapeutic target." (PMID 33391471, 2021). "Functional experiments further confirmed that MYDGF is a key FAM-related biomarker that enhances lipid deposition by suppressing fatty acid oxidation, thereby accelerating tumor progression." (PMID 40539074, 2025). "Subsequent experiments validated that MYDGF served as a critical biomarker for FAM, promoting lipid deposition through inhibiting FAO, thereby accelerating tumor progression." (PMID 40539074, 2025). "Here, we investigate the mechanism by which MYDGF promotes the progression of HCC and how it affects the tumor microenvironment." (PMID 33391471, 2021). "In addition, our research showed that MYDGF could promote tumor angiogenesis." (PMID 33391471, 2021). "Currently, the potential role of MYDGF in HCC progression and tumor microenvironment remains largely unknown." (PMID 33391471, 2021).
cancer (9 papers, 2021 to 2025). A tumor composed of atypical neoplastic, often pleomorphic cells that invade other tissues. "Subsequently, MYDGF was identified in other tissues and linked to various human diseases, including heart failure, atherosclerosis, kidney dysfunction, inflammation, and cancer." (PMID 40806387, 2025). "Excluding cancer, MYDGF secretion has been demonstrate to ameliorate these diseases through its anti-apoptotic and anti-inflammatory effects and tissue repair properties." (PMID 40806387, 2025). "MYDGF is overexpressed in different types of cancer cells and silencing it has been shown to decrease cancer cell proliferation." (PMID 39194522, 2024). "We speculated that MYDGF might influence proliferation by promoting cancer stem-like properties in HCC." (PMID 33391471, 2021). "In contrast, MYDGF did not induce proliferation of the cancer cell line HepG2, possibly because this immortalized cell line did not reflect the situation of adult human hepatocytes." (PMID 38316785, 2024).
cardiovascular diseases (3 papers, 2024 to 2025). "Since the formal name MYDGF was used, the effect of MYDGF on cardiovascular disease has been explored." (PMID 39030488, 2024). "Myeloid‐derived growth factor (MYDGF), a novel secreted protein, plays important roles in multiple cardiovascular diseases, but the function of MYDGF in tubular epithelial cells remains unknown." (PMID 39587987, 2025). "Therefore, MYDGF may play a beneficial role in cardiovascular disease through a variety of mechanisms, including improving endothelial cell function, reducing cardiomyocyte apoptosis, promoting cardiomyocyte regeneration, and inhibiting cardiac fibrosis." (PMID 39030488, 2024).
metabolic disorders (3 papers, 2023 to 2024). "Recent studies have shown that MYDGF has potent cardiac myocyte-protective and angiogenic activities, offering protection against cardiovascular and metabolic diseases." (PMID 39497829, 2024). "Recent studies have also shown that MYDGF is involved in multiple metabolic disorders, including glucose and lipid metabolism, non-alcoholic fatty liver disease (NAFLD), and bone metabolism." (PMID 39030488, 2024).
MYDGF also shares sentences with these, for which no sentence is quoted: acute myocardial infarction (2 papers); non-alcoholic fatty liver disease (2); alcoholic fatty liver disease (1); chronic myeloid leukemia (1); glioma (1); glomerular disease (1); infection (1); kidney diseases (1); kidney injury (1); leukemia (1); liver fibrosis (1); lymph node metastasis (1); melanoma (1); osteoarthritis (1); Ventricular hypertrophy (1).